BCL2 (BCL2 apoptosis regulator)
Diseases named in the same sentence as BCL2 in open-access papers (continued):
Sharing a sentence is not in itself a finding about the gene and the disease.
leiomyosarcoma (6 papers, 1999 to 2023). An uncommon, aggressive malignant smooth muscle neoplasm, usually occurring in post-menopausal women. "Uterine leiomyosarcoma (uLMS) may show loss of expression of B-cell lymphoma-2 (Bcl-2) protein." (PMID 35344084, 2023). "bcl-2 protein was expressed in nearly all benign smooth muscle tumours but in only 57% of leiomyosarcomas." (PMID 10408415, 1999). "The Bcl-2 was expressed more in leiomyosarcoma than in leiomyosarcoma and STUMPs." (PMID 37629661, 2023). "Our results suggest that bcl-2 is frequently expressed in human uterine smooth muscle tumours, and that its expression may correlate with a favourable prognosis in patients with uterine leiomyosarcoma." (PMID 10408415, 1999). "Moreover, DF45, BCL2 and DFF40 underexpression has been reported in numerous malignancies, including uterine leiomyosarcomas." (PMID 29653556, 2018).
lung squamous cell carcinoma (6 papers, 1997 to 2024). "In lung squamous cell carcinoma, it promotes proliferation, migration, and tumor progression by modulating the expression of Bcl-2 and Bax, enhancing ITGB8 expression, and binding to miR-299-3p, resulting in elevated MAP3K2 expression." (PMID 38612418, 2024). "TLR7 is also expressed in adenocarcinoma and squamous-cell carcinoma of the lung and promotes cancer cell survival through NF-κB activation and upregulation of Bcl-2." (PMID 34573939, 2021). "As expected, PML and BCL2 were not correlated (Spearman’s r = 0.092, p = 0.219) in the lung squamous cell carcinoma samples." (PMID 28332630, 2017).
odontogenic cyst (6 papers, 2018 to 2025). A cyst in the jaw that arises from tissues of tooth development. "The literature also compared the expression of Bcl-2 in OKCs/S and OKCs/Si with three other odontogenic cysts." (PMID 40818142, 2025). "This review revealed that Bcl-2 is expressed higher in AM than in OKCs, but Bcl-2 is expressed significantly higher in OKCs compared to other odontogenic cysts, such as OOCs, DCs, and RCs." (PMID 40818142, 2025). "To summarize, the study strengthens that the strong diffuse transepithelial CK17 and basal bcl2 are typical of OKCs, but also highlights that these patterns of staining, although to a lesser intensity and extent, can be seen in other odontogenic cysts, too." (PMID 32632899, 2020). "A strong bcl2 expression was also described in a botryoid odontogenic cyst reported recently, being the only case studied in this respect we could identify." (PMID 32632899, 2020). "Therefore, a low Ki-67 labeling index and lack of Bcl-2 expression in multiple OOC indicated mild biological behavior of odontogenic cysts." (PMID 36242048, 2022).
periodontal disease (6 papers, 2006 to 2024). "Moreover, the finding that tissue injury is associated with elevated Bcl-2 activation could open up new diagnostic possibilities and therapeutic strategies to prevent tissue destruction in periodontal disease." (PMID 16787530, 2006). "Bcl-2 expression has been identified in patients suffering from periodontal disease, but also in healthy patients, which has led to the association of inflammatory processes with the onset of periodontal disease." (PMID 34683807, 2021). "The aim of this study is to compare the expression levels of s100, bcl2 and MPO in gingival tissues on different stages of periodontal disease and compared to the giant-cell epulis." (PMID 26251029, 2015). "The data presented herein refer to CD3+ T cells and demonstrate that higher levels of HmuY-induced Bcl-2 expression were obtained in cells derived from CP subjects in comparison to individuals without periodontal disease (NP) (P = 0.043)." (PMID 24025186, 2013).
pituitary adenomas (6 papers, 2000 to 2025). "For example, trefoil factor 3 (TFF3) is an apoptosis-related protein, and its knockout in human pituitary adenoma cell line decreased the levels of apoptosis-related proteins Bcl-2 and caspase-3, and increased the levels of Bax and cleaved caspase-3." (PMID 31649621, 2019). "Furthermore, our data demonstrate that Magmas over-expression inhibits Staurosporine-induced apoptosis by hampering cytochrome c release from mitochondria in rat GH/PRL secreting pituitary adenoma cells, influencing Bax and Bcl2 modulation by pro-apoptotic stimuli." (PMID 24069394, 2013). "In the central nervous system, it was recently demonstrated that resveratrol decreased Bcl-2 expression and viability in GH3 pituitary adenoma cells of rats." (PMID 25483559, 2015).
polycystic ovary syndrome (6 papers, 2020 to 2025). A disorder that manifests as multiple cysts on the ovaries. "In a rat model of polycystic ovarian syndrome, genistein enhanced Bcl-2 expression and suppressed Bax in ovarian granulosa cells." (PMID 41433336, 2025). "Studies involving kisspeptin and apoptosis are inconsistent, but some have already demonstrated roles in attenuating apoptosis in neurons and in granulosa cells in rat polycystic ovary model, which also showed an increase in BCL-2, considered an antiapoptotic factor." (PMID 38338793, 2024).
prostate adenocarcinoma (6 papers, 2001 to 2023). "Moonlight also identified BCL2 as a tumor suppressor in prostate adenocarcinoma with promoter hypermethylation, deletion, and associated with increased apoptosis (, 9)." (PMID 31900418, 2020). "First, we analyzed mRNA and protein level of BCL2 in the TCGA provisional prostate adenocarcinoma dataset with clinical information." (PMID 32685011, 2020). "Treatment with 70% ethanol extracts of 228 μg/mL licorice for 24 h in LNCaP prostate adenocarcinoma cells induced autophagy‐related cell death by downregulating the Bcl‐2 protein and inhibiting the mTOR pathway." (PMID 28675698, 2017). "We observed a significant difference in the bcl-2 protein expression between the two groups of patients with adenocarcinoma of the prostate." (PMID 11500787, 2001). "In the TCGA provisional prostate adenocarcinoma dataset, KLF5 mRNA levels co-expressed with that of BCL2 with Pearson co-efficient value equal to 0.49 (p-value < 0.0001), which indicates an intermediate correlation." (PMID 32685011, 2020).
retinal ischemia (6 papers, 2009 to 2025). A ischemic disease that involves the retina. "Overall, our study suggested that tFNAs-siRUNX1 can mitigate Bcl-2/Bax-mediated apoptosis, leading to a partial reduction in initial perfusion loss or vascular breakdown that ultimately results in retinal ischemia." (PMID 40105819, 2025). "It clearly finds an association with an increase in Bax with a decrease in Bcl-xL expression and negates any involvement of Bak and Bcl-2 regulations in the damage induced by retinal ischemia 24 h after reperfusion." (PMID 19862336, 2009). "In another report, retinal ischemia was shown to induce an initial decrease in Bcl-2 mRNA expression followed by a later increase in its expression." (PMID 19862336, 2009). "The retinal ischemia–reperfusion injury rats exhibited elevated levels of the apoptotic proteins cleaved-caspase-3, caspase-3, and Bax, alongside reduced expression of the anti-apoptotic protein Bcl-2." (PMID 40610544, 2025).
schistosomiasis (6 papers, 2018 to 2025). An infectious disease caused by parasitic trematodes of the genus Schistosoma that colonize human blood vessels and release eggs that can cause granulomatous reactions leading to acute (swimmer's itch or acute schistosomiasis syndrome) or chronic disease.
Seizure (6 papers, 2013 to 2025). A seizure is an intermittent abnormality of nervous system physiology characterized by a transient occurrence of signs and/or symptoms due to abnormal excessive or synchronous neuronal activity in the brain. "Seizure-induced neuronal death features excitotoxic necrosis and apoptosis-associated signaling pathways, including activation of multiple members of the Bcl-2 gene family." (PMID 23882182, 2013). "Seizures cause up-regulation of anti-apoptotic Bcl-2, Bcl-w and Mcl-1." (PMID 23882182, 2013). "Previous investigations have suggested that in KA-induced epileptic seizure model, the protective protein Bcl-2 is down-regulated, and apoptosis occurs, consequently (Zhang, Yan, Wu, Li, & Zhang, 2011)." (PMID 32483474, 2020). "The Bcl-2 and caspase families analyzed in neocortex samples surgically removed from TLE patients with intractable seizures found significantly higher levels of antiapoptotic Bcl-2 and Bcl-xL compared to autopsy controls." (PMID 25614776, 2014). "Mice with genetic deletion or alteration of Bad (BCL-2 agonist of cell death) exhibit altered brain-cell fuel metabolism, accompanied by resistance to acutely induced epileptic seizures; this seizure protection is mediated by ATP-sensitive potassium (KATP) channels." (PMID 29368690, 2018).
varicocele (6 papers, 2018 to 2026). A condition characterized by the dilated tortuous veins of the spermatic cord with a marked left-sided predominance. "On the other hand, the mRNA level of Bcl2 was remarkably higher than in the control subgroup compared to the varicocele and lycopene subgroups (p < .05)." (PMID 35592276, 2022). "Our finding also indicated that the expressions of HIF1‐α and Bax mRNA were higher and Bcl2 was lower in the testis tissues of the rats with varicocele than healthy rats (p < .05)." (PMID 35592276, 2022). "The results showed a significant decrease in the sperm viability, membrane integrity, Johnson's score, and the expression of the Bcl2 gene in the varicocele group compared to the control group." (PMID 35592276, 2022). "The varicocele induction in rats considerably enhanced the ratio of Bax to Bcl-2 protein expression in the testicular tissues compared to the sham group (1.28 ± 0.08 vs. 0.20 ± 0.03, p < 0.001)." (PMID 36618833, 2022). "In this study, our findings showed a marked increase in the ratio of Bax to Bcl-2 protein expression levels in the testicular tissues of varicocele rats, which was remarkably reduced by the co-administration of subeffective doses of testosterone and NaHS." (PMID 36618833, 2022). "Varicocele-induced damage markedly increased and decreased the pro-apoptotic BAX and the anti-apoptotic Bcl-2 gene expression, respectively; this strongly suggests that the apoptotic process was stimulated in varicocele rats." (PMID 32466161, 2020). "However, the combined administration of testosterone and NaHS significantly decreased the Bax to Bcl-2 protein expression ratio in the testicular tissues compared to the varicocele group (0.16 ± 0.01, 95% CI: 0.53-0.95, p < 0.001)." (PMID 36618833, 2022). "In fact, Bcl-2 mRNA expression was significantly reduced in varicocele rats, whereas lycopene administration significantly increased its expression in both operated and contralateral testes, thus demonstrating that apoptotic pathway was reduced following lycopene treatment." (PMID 32466161, 2020). "There were no considerable differences in the ratio of Bax to Bcl-2 protein expression in the testicular tissues in the groups of testosterone (1.03 ± 0.13) and NaHS (1.19 ± 0.10) alone in comparison with the varicocele group." (PMID 36618833, 2022).
Acute B-Lymphoblastic Leukemia (5 papers, 2019 to 2023). "Dysregulation of the intrinsic BCL-2 pathway-mediated apoptosis cascade is a common feature of hematological malignancies including acute B-lymphoblastic leukemia (B-ALL)." (PMID 35778418, 2022).
acute liver failure (5 papers, 2012 to 2023). Rapid deterioration of liver function causing encephalopathy and coagulopathy. "It was reported that Oxymatrine combined with Compound Yinchen Granules reduced the Bax/Bcl-2 ratio to inhibit the apoptosis of liver cells in acute liver failure." (PMID 37600712, 2023). "In an acute liver failure setting, it was shown that miR-16 reduced hepatic apoptosis via the anti-apoptotic gene BCL2." (PMID 32365562, 2020). "In addition, in acute liver failure, inhibition of miR-15b reduced the hepatic apoptosis via BCL2 regulation and TNF-α production." (PMID 25323448, 2014). "The present study found that the level of mitochondrial Bcl-2 was significantly increased in liver of mice administered with APAP, indicating that Bcl-2 is not downstream target of the activated JNK during APAP-induced acute liver failure." (PMID 23272189, 2012).
adrenocortical carcinoma (5 papers, 2013 to 2025). "Our results show that Bcl-2 was decreased by Sal in adrenocortical carcinoma cells, a finding that is consistent with previous research." (PMID 34567111, 2021). "Specifically, in prostate cancer cells, laryngeal squamous cell carcinoma (LSCC), and adrenocortical carcinoma (ACC) SW-13 cells, miR-205 upregulation has been shown to significantly reduce both BCL-2 mRNA and protein expression levels." (PMID 41001034, 2025).
allergic asthma (5 papers, 2016 to 2025). A asthma with a basis in a pathological type I hypersensitivity reaction. "extract at the concentration of 100 μg/ml activates macrophages and modulates the TGF-β/Smad/Bcl2/caspase/LC3 and AMPK/PI3K/Akt/p38-NF-κB cascades, improving lung injury and inflammatory aggravation in a murine allergic asthma model induced by OVA-LPS." (PMID 39263346, 2024). "extracts can regulate the AMPK/PI3K/AKT/p38-NF-κB and TGF-β/Smad/Bcl2/caspase/LC3 signaling pathways to produce cascade reaction and activate macrophages, thus alleviating allergic asthma and lung infection induced by OVA." (PMID 35431951, 2022).
brain tumors (5 papers, 2016 to 2025). "Of note, we observed a significant impact on the levels of Bcl-2 in both the types of brain tumor cells (GBM and LGG) undertaken in the present study." (PMID 39833890, 2025). "In these brain tumors miR-181a was shown to target the anti-apoptotic genes BCL2 and MCL1, and downregulated miR-181a reduced glucose deprivation-induced apoptosis and caused mitochondrial dysfunction in astrocytes." (PMID 27517749, 2016). "-In GSC cultures, the infection by ZIKV induced miR-34 expression, inhibiting the anti-apoptotic protein Bcl-2 and Numb, involved in GSC invasion.-In mouse models, ZIKV reduced brain tumor size and metastasis." (PMID 40141375, 2025). "Further, the protein expression of BCL2 and BAX in brain tumors of GL261-Vector-bearing or GL261-LRIG3-bearing mice were detected." (PMID 36639372, 2023). "Evidence in the literature indicates that DMC induced BCL-2-mediated G2/M arrest most effectively among CUR, DMC, and BDMC in brain tumors." (PMID 32188144, 2020).
chronic atrophic gastritis (5 papers, 2017 to 2024). Atrophic gastritis that is persistent and long-standing. "In tumor adjacent mucosa, Bcl-2 was found in lower levels compared to GC but to our knowledge no study has so far focused on Bcl-2 in atrophic gastritis and intestinal metaplasia in tumor adjacent mucosa." (PMID 28662697, 2017).
Chronic colitis (5 papers, 2018 to 2024). A chronic inflammatory disease of the large intestine (colon, cecum and rectum). "Nonetheless, BMS-477118 at doses of 5 or 10 mg/kg decreased the ratio of Bax/BCL-2 and A-caspase-3 levels compared to the untreated chronic colitis group." (PMID 39359253, 2024). "This is in line with the increase of Bcl-2 in the diet switch group suggestive for a possible mechanism by which the AIN93G diet counteracts chronic colitis." (PMID 31877961, 2019). "Excessive activation of STAT3 mediated by increasing IL-6 enhances the expression of antiapoptotic factors such as Bcl-2, which contributes to the sustainability of chronic colitis." (PMID 30498394, 2018). "Interestingly, it has recently been reported that a Bcl-2 antagonist prevents fibrosis in a murine model of chronic colitis." (PMID 35448666, 2022).
Crohn disease (5 papers, 2014 to 2020). A gastrointestinal disorder characterized by chronic inflammation involving all layers of the intestinal wall, noncaseating granulomas affecting the intestinal wall and regional lymph nodes, and transmural fibrosis. "Expression of the BCL2 gene in the peripheral blood lymphocytes of patients with Crohn’s disease was significantly and nearly three times higher than in controls (p = 0.022)." (PMID 31159239, 2019). "Indeed, intestinal lymphocytes of Crohn's disease patients have been shown to have upregulated expression of antiapoptotic Bcl-2 and Bcl-XL and downregulated expression of proapoptotic Bax." (PMID 30515402, 2018). "Interestingly, higher levels of the BCL2 protein was registered in freshly isolated Crohn’s disease patient polymorphonuclear neutrophils, in contrast to controls, in which BCL2 protein was undetectable." (PMID 27486433, 2016).
endometrial polyp (5 papers, 2005 to 2020). A benign nodular lesion protruding above the surface of the endometrium. "A localized increase in Bcl-2 expression and consequential decline or cessation of apoptosis are important mechanisms underlying the pathogenesis of endometrial polyps." (PMID 24314145, 2013). "Hormone replacement therapy (HRT) impacts on the expression of Ki-67, Bcl-2, and c-erb.B2 in endometrial polyps during menopause and may cause endometrial polyp involution by decreasing proliferation and stimulating apoptosis." (PMID 24314145, 2013). "A localized increase in Bcl-2 expression and consequential decline or cessation of apoptosis may be another mechanism underlying the pathogenesis of endometrial polyps." (PMID 15703068, 2005). "Some studies have suggested that endometrial polyp growth occurs due to decreased apoptosis, characterized by increased Bcl-2 expression." (PMID 32215462, 2020). "In the present sample, Bcl-2 was expressed in the endometrial polyps of all patients (users and nonusers of tamoxifen)." (PMID 32215462, 2020). "However, estrogen may have a role in the development of post-menopausal endometrial polyps, either by direct stimulation of localized proliferation or by stimulation of proliferation via other pathways, such as activation of Ki67 or through inhibition of apoptosis via Bcl-2." (PMID 24314145, 2013).
Hypoglycemia (5 papers, 2009 to 2022). A decreased concentration of glucose in the blood. "To understand the underlying mechanisms of VEGF-mediated protection against hypoglycemia, we analyzed Glut-1 and Bcl-2 protein levels by western blot in response to VEGF during hypoglycemia." (PMID 25761767, 2015).
invasive carcinoma (5 papers, 2002 to 2019). A carcinoma that is not confined to the epithelium, and has spread to the surrounding stroma. "This is compatible with our finding of co-localization of TFF3 and BCl2 in residual invasive carcinoma in incomplete pathological response group." (PMID 30744593, 2019). "Bcl-2 expression has also been described in the majority (up to 85%) of colorectal adenomas, with reduced expression on progression to invasive carcinoma." (PMID 16029489, 2005). "Bcl-2 immunoreactivity was higher in mild dysplasia than in severe dysplasia or invasive carcinoma (data not shown)." (PMID 30886526, 2019).